VCAM1 (vascular cell adhesion molecule 1)
Diseases named in the same sentence as VCAM1 in open-access papers (continued):
Sharing a sentence is not in itself a finding about the gene and the disease.
cancer (continued). "Early studies have observed that vascular cell adhesion molecule-1 (VCAM-1) is aberrantly expressed in several cancers, including GBM." (PMID 33066460, 2020). "NF-κB is a vital transcriptional factor that mediates VCAM-1 transcriptional activity and cancer metastasis." (PMID 32847038, 2020). "Activated VLA-4 (also known as α4β1) enables transient interactions with VCAM-1 expressed on the cell surface of cancer endothelium supporting adhesion and transmigration." (PMID 33262763, 2020). "Most of the genes in the subnetworks were inflammatory cytokines and participated in TNF signaling pathways and pathways in cancer, such as Ccl2, Ccl20, Csf1, Cx3cl1, Cxcl1, Cxcl3, Il6, Birc3, Map3k8, Nos2, Nfkb2, Tnfrsf1b, and Vcam1." (PMID 33042984, 2020). "First, intercellular adhesion molecule-1 (ICAM-1) and vascular cell adhesion molecule-1 (VCAM-1) are needed for the extravasation of T cells and upregulation of ICAM-1 has been associated with good prognosis of cancer patients." (PMID 33614478, 2020). "VCAM-1 (Vascular Cell Adhesion Molecule 1) overexpression is related to angiogenesis and metastasis in cancer, including GC; in which both local expression in gastric tissue and serum levels are directly associated with poor prognosis." (PMID 32117120, 2020). "Anti-VCAM-1 aptamer would be a promising candidate as a therapeutic agent to inhibit or suppress VCAM-1 expression on cancer cell surfaces." (PMID 32751068, 2020). "Overall, this facilitates the transmigration of cancer cells (via an interaction of endothelial cell VCAM1 with cancer cell α4-integrin) and immune cells into the circulation, and homing to distant metastatic sites." (PMID 32575680, 2020). "Integrins (such as αvβ3 and β5 integrins), ligand sialyl Lewis, and endothelial receptors (ICAM-1,VCAM-1) are also widely reported to contribute to the adhesion of cancer cells to endothelia in and expressed on several cancer cells’ surface." (PMID 33379338, 2020). "VCAM-1 overexpressed on the surface of cancer cells binds with the counter receptor α4β1integrin and activated phosphoinositide 3-kinase activity, which led to the further survival of the cancer cells." (PMID 32751068, 2020). "This study confirmed that the enforced expression of VCAM1 increased the migration and invasion ability of cancer cells in vitro and obviously generated more and larger metastatic nodules in the lung and liver than did control cells." (PMID 32793471, 2020). "Soluble form of VCAM-1 (sVCAM-1), which is cleaved from cell surfaces, is detected in the serum of several types of cancer patients and was reported as a staging or prognosis marker in several types of cancer." (PMID 33273652, 2020). "Cell Viability and luciferase assay of 4T1-Luc2 cancer cells in the presence of anti-VCAM-1 ssDNA or anti-IL4Rα RNA aptamers was assessed by monitoring the changes in the absorbance and the fluorescence of Alamar blue dye." (PMID 32751068, 2020). "VCAM‐1‐expressing carcinoma cells are able to obtain the ability to metastatic colonization by activating AKT signalling." (PMID 32537867, 2020). "Firstly, it was found that M2 macrophages infiltration was increased in cancer tissues, and the VCAM-1 expression and CD206+ macrophages infiltration were correlated based on immunohistochemical analysis." (PMID 30894509, 2019). "The Cancer Genomic Atlas (TCGA) database was analyzed to evaluate the prognostic role of VCAM-1 in TNBC." (PMID 31340603, 2019). "VCAM-1 is inducible and predominantly expressed in endothelial cells and also on the surface of other cells, including macrophages and cancer cells." (PMID 31035617, 2019). "FAK activity controls vascular cell adhesion molecule-1 (VCAM-1) and E-selectin in mouse fibroblasts and cancer cells." (PMID 31110200, 2019). "The adhesion molecules ICAM-1 and VCAM-1 are mediating the cell adhesion of cancer cells, lymphocytes and other cells to the vascular endothelium." (PMID 31731625, 2019).
cancer (continued). "In the lungs VCAM-1 binds to α4β1 integrin expressed on macrophages triggering the activation of the PI3K/Akt survival pathway in cancer cells." (PMID 31340603, 2019). "Future studies with these specific blockades will create new avenues for better understanding the regulatory mechanisms of VCAM-1 as a potential therapeutic target in immunological disorders and cancer." (PMID 29614819, 2018). "This expression of ABCG2 was induced by juxtacrine interactions between VCAM-1 on cancer cells and VLA-4 on macrophages." (PMID 28969049, 2017). "Here, DTCs, which have high expression of VCAM-1, engage α4-integrins on MAMs to initiate prosurvival signalling within cancer cells through the PI3K/Akt signalling pathway." (PMID 28210073, 2017). "VCAM-1 is overexpressed in several types of cancers, including renal, gastric, pancreatic, breast, and ovarian cancers." (PMID 28272300, 2017). "For example, in a bone metastasis dormancy model, VCAM-1 expression by cancer cells is shown to support reactivation of indolent cancer cells and bone metastasis by interacting with the microenvironment." (PMID 29197379, 2017). "This improves the direct contact between cancer cells and macrophages through VCAM1-α4 integrin mediated signalling and promotes cancer cell retention in the metastatic site." (PMID 28210073, 2017). "In order to investigate the effect of CBP501 on the interaction between cancer cells expressing VCAM-1 and macrophages expressing VLA-4, LDV-FITC was used to detect the expression of VLA-4 protein on the macrophage cell surface." (PMID 28969049, 2017). "The presence of VCAM-1 has been demonstrated on endothelial cells, macrophages, dendritic cells, and surface of cancer cells." (PMID 26881177, 2016). "Further, the Oncomine database, consisting of datasets derived from various microarray studies, provides evidence that VCAM-1 is significantly upregulated in various cancer types including brain, breast, ovarian, and esophageal carcinomas." (PMID 26881177, 2016). "ICAM-1 and VCAM-1 are two important cell surface adhesion molecules that are mainly expressed in endothelial cells to modulate the immune process and cancer cell adhesion to the endothelium." (PMID 26690142, 2015). "Integrin α4β1 and its adhesion receptor, cell adhesion molecule-1 (VCAM-1), were also reported to play a role in the interaction between cancer cells and the mesothelial cells." (PMID 26223322, 2015). "It is generally accepted that VCAM-1 facilitates cancer cell metastasis via enhancing adhesive ability of cancer cells." (PMID 26592552, 2015). "Recently, soluble forms of adhesion molecules, including ICAM-1 and VCAM-1, have been found in the serum of cancer patients, in the supernatant of cytokine-activated endothelial cells and in the culture medium of CRC cell lines." (PMID 26690142, 2015). "The expression of ICAM-1 and VCAM-1, which are regulated by the transcription factor NF-κB, in endothelial cells initiates the adhesion of cancer cells and monocytes to the endothelium." (PMID 26690142, 2015). "VCAM-1 is a key mediator of intercellular contact in tumors and has been suggested as a potential therapeutic target in cancer metastasis and GBM cell invasion." (PMID 25084358, 2014). "Resistin has been indicated to induce ICAM-1 and VCAM-1 expressions through transcription factor NF-κB in endothelial cells and to initiate the cancer cells and monocyte adhesion." (PMID 24555415, 2014). "Among them, VCAM-1 has garnered increasing attention in the anti-cancer field and recognized as a potential therapeutic target in metastasis." (PMID 23460862, 2013). "Blocking VCAM-1 on the endothelium surface but not ICAM-1 and E-selectin was shown to abolish the effect of such ROS on cancer cell binding, implying that ROS mediates cancer cell adhesion via VCAM-1-dependent mechanism." (PMID 23460862, 2013). "It has been suggested that the VCAM-1-CD49d interaction promotes cancer cell survival and migration." (PMID 24052950, 2013).
cancer (continued). "The number of CECs detectable in individuals has previously been found to be associated with the plasma levels of VCAM-1 and VEGF in cancer patients." (PMID 22731825, 2012). "High-molecular-weight-kininogen, apolipoprotein A1, soluble vascular cell adhesion molecule-1, plasminogen activator inhibitor-1, vitamin-D binding protein and vitronectin were decreased in the cancer group." (PMID 19400944, 2009). "Elevated levels of serum VEGF, E-selectin and VCAM-1, and of plasma PAI-1 and VEGF, have already been linked to a worse prognosis in a variety of cancers." (PMID 15354209, 2004). "VCAM-1 endothelial expression, as the previous adhesion molecules, exerts its anti-tumoral contribution through the recruitment of immune cells directed against cancer." (PMID 40071851, 2025). "Similarly, VCAM-1-functionalised nanosystems have also proven promising as a potential platform for cancer theranostics." (PMID 40095109, 2025). "Moreover, a substantial down‐regulation of VCAM‐1 within the microvessel was validated at protein level by immunostaining: upon co‐culture with A549 cancer cells, VCAM‐1 protein level in ECs decreased of two folds." (PMID 40348600, 2025). "However, VCAM-1 expression on endothelial cells favors a change in the immune microenvironment promoting T-cell infiltration of tumors and cancer control." (PMID 40071851, 2025). "Likewise, EpCAM+ITGAV+ cancer cells expressed higher levels of the plasticity genes Axl, Tnc, Itgb3, and Vcam1 than EpCAM+ITGAV− cancer cells, indicating that EpCAM+ITGAV+ cancer cells exhibit a hybrid E/M phenotype." (PMID 39075581, 2024). "The α4β1 integrin expressed by cancer cells may act as an alternative ligand for VCAM-1 to mediate the adhesion of cancer cells to the endothelium." (PMID 39035739, 2024). "Antibodies against VCAM-1 could have a range of clinical applications in cardiovascular disease, cancer, and inflammatory diseases." (PMID 39769411, 2024). "Further analyses revealed soluble VCAM-1 from PD cells recruited integrin α4β1-positive monocytic osteoclast precursors to the bone and the precursor-derived osteoclasts underwent osteoclastogenesis, a critical process for bone metastasis of cancer." (PMID 38786066, 2024). "Similarly to ICAM-1, VCAM-1 acts in the immune-endothelial communication system, contributing to inflammatory and immune processes and cancer metastasis." (PMID 38785560, 2024). "Studies have indicated that the α4β1 integrin on macrophage cell surface could actively bind to vascular cell adhesion molecule-1 (VCAM-1) on cancer cells." (PMID 39613774, 2024). "Interestingly, VCAM-1 is also an immunosuppressive and anti-inflammatory factor, in particular, it reduces T-cell infiltration to carcinoma lesions." (PMID 39767739, 2024). "In conclusion, PLGA nanoparticles containing VCAM-1 inhibitor Suc and chemotherapeutic Dox as therapy against primary tumors and their lung metastases provides a promising drug delivery strategy for the treatment of metastatic malignant tumors." (PMID 36839671, 2023). "Prior studies have indicated that integrin α4 and β1 on macrophages could interact with vascular cell adhesion molecule-1 (VCAM-1) on cancer cells." (PMID 38111068, 2023). "Moreover, the expression of integrin α4 and β1 on TAMs facilitates their interaction with VCAM-1 on cancer cells, thereby aiding the migration of cancer cells towards distant metastatic sites." (PMID 38111068, 2023). "These ligands in particular are such as those involved in the context of adhesion molecules expressed on CD133+/− (CXCR4-) medullablastoma cancer stem cells (HTB-186 that expressed ICAM-1, VCAM-1, LFA-3), susceptible to natural killer (NK) cell mediated activity-killing." (PMID 38155835, 2023). "EGF treatment upregulates VCAM-1 and enhances the interaction between macrophages and cancer cells." (PMID 37296983, 2023).
cancer (continued). "The strategies include targeting vascular endothelial growth factor/receptors, αvβ3 integrin receptors overexpressed on endothelial cells in various types of cancer, as well as vascular cell adhesion molecule-1 (VCAM-1) and intercellular adhesion molecule-1 (ICAM-1)." (PMID 37376203, 2023). "VCAM1 as one of adhesion molecules contributes to critical physiologic functional roles in cancer metastasis and therapy resistance, and is the only one showing a significantly higher expression level in RCC tissues than in normal tissues both at protein and mRNA level." (PMID 37622107, 2023). "The mass spectrum analysis displayed many antigens of carrier macrophages were cryopreserved after the liquid nitrogen post-treatment, especially for integrins which could tether cancer cells via VCAM-1 31,32." (PMID 37673934, 2023). "On one hand, TNF-α promotes cancer cells survival by activating TNFRs, vascular cell adhesion molecule 1 (VCAM1) and altering the protein complex I and II (complex I consists of TRADD, TRAF2 and RIP and Complex II that consists of TRADD, RIP, FADD and caspase-8)." (PMID 35954156, 2022). "Both VCAM1 and PDGFA are associated with angiogenesis and involved in cancer development." (PMID 35565312, 2022). "Then, the aim of this study was also to test whether PD can modulate the expression of adhesion molecules, such as ICAM-1, VCAM-1, and E-selectin, induced in HUVECs by the SN of LPS-stimulated HT-29 cancer cells." (PMID 35955576, 2022). "Cannabigerol-specific effects included the inhibition of angiopoietin-1, MMP3 and VCAM-1, indicating that its anti-cancer effects may be mediated by the modulation of vascular-immune interactions." (PMID 36923728, 2022). "In addition, VCAM1 is a key element of the inflammation pathway, contributing to several immunological disorders as well as cancer." (PMID 36513788, 2022). "Thus, the binding to endothelial adhesion molecule VCAM-1 by TAPLT is closely associated with their capacity of protecting EC against TCM-mediated permeation and pro-inflammatory activation that facilitate cancer metastasis through the endothelium." (PMID 35408794, 2022). "Interestingly, in PT2 the transcriptional signature was one of inflammation and regeneration gene expression (SOX9, IL32, and VCAM1), which has been related to carcinogenesis and cancer progression." (PMID 36180422, 2022). "ICAM1, E-selectin, VCAM1, neuronal cadherin (N-cadherin), and integrins are among the best characterized molecules of the ECs involved in cancer cell adhesion onto endothelium and cancer cell extravasation." (PMID 36248978, 2022). "Furthermore, interaction of metastatic cancer cells with the hematopoietic niche is mediated by α4β1‐vascular cell adhesion molecule 1 (VCAM1), chemokines like CXCL12, BMP, Notch, Nestin, and osteopontin." (PMID 35506376, 2022). "Moreover, sustained Notch1 signaling in ECs, induced by cancer cells, drives cytokine and VCAM1 expression and the infiltration with myeloid cells, which facilitates metastasis." (PMID 34073394, 2021). "The α4β1 integrin on the RAW264.7 membrane is activated by vascular cell adhesion molecule-1 (VCAM-1), which is expressed at high levels on metastatic cancer cells, thereby increasing the ability of DPLGA@[RAW-4T1] NPs to specifically target metastatic cancer tissue." (PMID 34142930, 2021). "Adhesion interaction between metastatic cancer cell and activated endothelial cells mediated by integrins and vascular cell adhesion molecules (in particular VCAM-1) upon activation by inflammatory stimuli may represent a key mechanism." (PMID 33294440, 2020). "Recently, VCAM‐1 has been demonstrated to promote cell adhesion and migration of cancer metastasis." (PMID 32741140, 2020).
cancer (continued). "Several different adhesion molecules regulate cancer migration and invasion during the metastatic process, including vascular cell adhesion molecule 1 (VCAM-1), an inducible surface glycoprotein from the immunoglobulin superfamily, which is involved in numerous biological activities." (PMID 32847038, 2020). "Additionally, VCAM-1, itself expressed on cancer cells, has been determined as a driver of metastatic dissemination due its competence to bind to α4ß1 found on the endothelium in lymph nodes." (PMID 30657059, 2019). "However, the molecular mechanism of VCAM-1 on cancer cell biological behaviors deserves further research." (PMID 29670110, 2018). "VCAM-1 is a potential therapeutic target in immunological disorders and cancer." (PMID 29614819, 2018). "Vascular cell adhesion molecule 1 (VCAM-1) is overexpressed in varieties of cancers." (PMID 29853809, 2018). "Various cell adhesion molecules on the endothelium, such as intercellular adhesion molecule 1 (ICAM-1), vascular cell adhesion protein (VCAM-1), E-selectin or N-cadherin as well as integrins expressed on cancer cells have been reported to mediate cell adhesion of cancer cells onto endothelial cells." (PMID 30204757, 2018). "This hypothesis is also supported by the VCAM-1 immunofluorescent staining results showing a pro-inflammatory phenotype in the pulmonary endothelium as early as 2 weeks following cancer cell transplantation, at the early stage of the metastatic process." (PMID 29788918, 2018). "The aim of this study was to explore the possibility of a noninvasive and semiquantitative method for targeting VCAM-1 in tumors, which may allow early cancer diagnosis, more precise prognosis, and targeted treatment options." (PMID 29853809, 2018). "Furthermore, IL-1β promotes cancer cell adhesion and hepatic metastases by up-regulation of vascular cell adhesion molecule (VCAM-1) on hepatic sinusoidal endothelium." (PMID 30042333, 2018). "Taken together, these results show that CBP501 can suppress ABCG2 expression in cancer cells by suppressing cell-cell interactions between cancer cells expressing VCAM-1 and macrophages expressing VLA-4, at least by reducing the expression levels of these surface molecules." (PMID 28969049, 2017). "We hypothesized that interaction between cancer cells expressing VCAM-1 and macrophages expressing VLA-4 might induce expression of ABCG2 in the cancer cells." (PMID 28969049, 2017). "CBP501 reduced the expression levels of VCAM-1 on cancer cells and β1-integrin on macrophages." (PMID 28969049, 2017). "In addition, juxtacrine interaction between cancer cells expressing VCAM-1 and macrophages expressing VLA-4 induces expression of the CSC-like cell marker ABCG2, which relates to drug resistance, on cancer cell surfaces." (PMID 28969049, 2017). "CBP501 might therefore suppress ABCG2 expression on cancer cells not only through reduction of expression levels of VCAM-1 and β1-integrin, but also through its suppression of integrin function." (PMID 28969049, 2017). "Moreover, CBP501 suppressed expression of ABCG2, a marker for CSCs, by inhibiting the interaction between cancer cells expressing VCAM-1 and macrophages expressing VLA-4." (PMID 28969049, 2017). "Indeed, ICAM-1 and VCAM-1 expression correlates with increased metastasis and determines malignant potential of cancer [29." (PMID 27409174, 2016). "ICAM1 and VCAM1 are considered to be important in the process of malignant tumor growth." (PMID 26239324, 2015). "Both ICAM-1 and VCAM-1 play a crucial role in cancer metastasis." (PMID 26690142, 2015). "However, the present study shows that resistin not only induces ICAM-1 and VCAM-1 expression in CRC cells but also mediates cancer cell adhesion to the endothelium." (PMID 26690142, 2015).